CGAS (cyclic GMP-AMP synthase)
Diseases named in the same sentence as CGAS in open-access papers (continued):
Sharing a sentence is not in itself a finding about the gene and the disease.
inflammatory skin disease (2 papers, 2021 to 2025). Inflammatory skin disorders covers a broad category that includes many conditions ranging in severity, from mild itching to grave medical health complications These disorders are common in people of all ages and races. "Taken together, these results indicate that activation of the innate immune system via the cGAS/STING pathway is a critical component of the inflammatory skin disease seen in Dnmt1Δ/Δep mice." (PMID 34586646, 2021). "Potential inhibitors targeting cGAS-STING for the treatment of inflammatory skin diseases." (PMID 40552157, 2025). "As research continues to advance the clinical applications of cGAS-STING pathway modulation, this therapeutic approach holds broad potential for treating inflammatory skin disorders." (PMID 40552157, 2025).
interstitial lung disease (2 papers, 2025 to 2026). A diverse group of lung diseases that affect the lung parenchyma. "We previously demonstrated that interstitial lung disease developed largely independent of the IFN I signaling, and occurs in the absence of cGAS, IRF3, IRF7, and of IFNAR1." (PMID 40111902, 2025).
kidney (2 papers, 2023 to 2024). "The activated cGAS-STING pathway then recruits inflammatory cells into the prostatic stroma via the secretion of cytokines (IFN-β), thereby causing the development of prostatitis." (PMID 38491517, 2024). "The cGAS-STING pathway activated by dual deficiency of dihydrotestosterone and melatonin plays a comprehensive inflammatory role in SD-related prostatitis." (PMID 38491517, 2024). "Overall, we hypothesized that insufficient sleep may induce prostatitis by regulating melatonin-mediated activation of the cGAS-STING pathway." (PMID 38491517, 2024). "Proteomic analysis revealed that the cGAS-STING pathway may play a significant role in inducing prostatitis." (PMID 38491517, 2024). "Thus, we assessed whether blocking the cGAS-STING pathway via MT supplementation would alleviate prostatitis in sleep-deprived mice." (PMID 38491517, 2024). "The expression and downstream proteins of cGAS were inhibited, thereby suppressing the cGAS-STING pathway, which resulted in the alleviation of prostatitis in sleep-deprived mice." (PMID 38491517, 2024). "The activation of the cGAS-STING pathway in sleep-deprived mice was obviously inhibited by recovery sleep, which has significant implications for improving prostatitis." (PMID 38491517, 2024). "Correspondingly, the released mt-DNA activated the cGAS-STING pathway, subsequently enhancing the recruitment of inflammatory cells into the prostate, leading to the formation of an inflammatory microenvironment (prostatitis)." (PMID 38491517, 2024). "Therefore, inhibiting the cGAS-STING signalling pathway and increasing MT and DHT levels are potential strategies for treating prostatitis induced by sleep deprivation." (PMID 38491517, 2024). "Therefore, cGAS-STING may be involved in the induction and regulation of prostatitis progression." (PMID 38491517, 2024). "We used cGAS knockdown and MT supplementation to inhibit the cGAS-STING pathway in sleep-deprived mice, and the results showed that prostatitis was not induced during the same period." (PMID 38491517, 2024).
kidney damage (2 papers, 2022 to 2025). "Cytosolic mtDNA activates the cyclic GMP-AMP synthase (cGAS)-stimulator of interferon genes (STING) pathway, resulting in kidney damage." (PMID 35160028, 2022).
Legionella infection (2 papers, 2018 to 2021). "Although DNA-PK has been linked to viral and bacterial DNA-dependent cGAS/STING activation and STING-independent pathogen recognition pathways, it has never before been examined for a role in Legionella infection." (PMID 34280250, 2021).
lentivirus infection (2 papers, 2016 to 2022). Virus diseases caused by the Lentivirus genus. "In sum, these observations provide genetic evidence that cGAS, STING, and signaling through the type I IFN receptor are required for SAMHD1-dependent myeloid cell activation upon lentivirus infection." (PMID 27477283, 2016).
leukopenia (2 papers, 2021 to 2025). "Severity of CLP in cGAS-/- mice was less severe than in wildtype (WT) mice, as indicated by mortality, serum LPS, cfDNA, leukopenia, cytokines (TNF-α, IL-6 and IL-10), organ histology (lung, liver and kidney) and spleen apoptosis." (PMID 34768881, 2021).
liver cirrhosis (2 papers, 2025 to 2026). "During the progression of liver cirrhosis, mitochondrial injury in hepatocytes promotes the release of mtDNA‐enriched EVs, which further activate cGAS‐STING signaling in skeletal muscle macrophages by shedding mtDNA." (PMID 39804962, 2025).
metastatic cancer (2 papers, 2020 to 2023). A carcinoma which has spread from the original site of growth to another anatomic site. "Although there are many reports of cGAS-STING pathway for anti-tumor effects, it was also reported that activation of the cGAS-STING axis in metastatic cancer caused chronic inflammation in tumor tissues, which enhanced cancer cell survival and metastasis." (PMID 33633744, 2020). "Together, transcriptome, proteome and signaling analyses suggest that cGAS binds to DNA in the cytosol of 66cl4 cells in culture and cause a constitutive IFN-I response in these metastatic cancer cells that is not detected in the non-metastatic cells." (PMID 36882786, 2023).
microcephaly (2 papers, 2021 to 2022). A congenital or acquired developmental disorder in which the circumference of the head is smaller than normal for the person's age and sex. "Based on the mechanism revealed in this study, it is possible that microcephaly resulting from Zika infection or loss of ZNF335 or ANKLE2 may be driven by cGAS/STING-dependent apoptosis of neuronal progenitors and/ or CNS immune cells." (PMID 36202870, 2022). "Remarkably, A‐T BOs recapitulate the microcephaly phenotype previously reported in A‐T patients, and chemical inhibition of cGAS and STING via aspirin or H‐151, respectively, rescued both BO size defects and entry into cellular senescence." (PMID 34459078, 2021). "Should our mechanism extend to neuronal progenitors or CNS immune cells, it may be possible to pharmaceutically prevent microcephaly in these specific instances by inhibition of the cGAS/STING pathway." (PMID 36202870, 2022).
neuroblastoma (2 papers, 2023 to 2026). Neuroblastoma (NB) is the most common solid, extracranial childhood tumor. "We first identified a CpG island that covers the promoter and the first exon of cGAS locus and found that it was hypermethylated in the COLO320, GBM, and neuroblastoma cell lines, correlating with the absence of cGAS in these cells." (PMID 41509453, 2026).
Opportunistic infection (2 papers, 2022 to 2023). An infection that is caused by a pathogen that would generally not be able to cause an infection in a host with a normal immune system. "However, Our study also demonstrates that the cGAS/STING pathway in ΔF mice can be restored by treatment with agonists and that its activation re-established the defences host response against opportunistic infections." (PMID 36923406, 2023). "Compared to blocking common natural immune targets, such as TBK1 or IFNs, inhibition of cGAS-STING has less risk of immunosuppression and opportunistic infections without keeping the other PRR systems intact." (PMID 36172373, 2022).
pancreatitis (2 papers, 2020 to 2025). Inflammation of the pancreas. "As for some diseases with inflammatory responses involved, the acute phase of pancreatitis causes dying acinar cells to produce free dsDNA, which activates cGAS-STING signaling in macrophages, and exacerbates inflammation severity." (PMID 32411126, 2020). "However, in the chronic phase of pancreatitis, cGAS-STING activation decreases pancreatic inflammation, which may be mediated by limiting Th17 response." (PMID 32411126, 2020).
proteinopathies (2 papers, 2020 to 2021). "Taken together, our results suggest that the activation of mtDNA release and cGAS-STING signaling is essential for maintaining mitochondrial function in TDP-43-induced proteinopathies." (PMID 35052586, 2021).
renal carcinoma (2 papers, 2021 to 2022). A carcinoma arising from the epithelium of the renal parenchyma or the renal pelvis. "Thus, a further independent validation cohort is warranted to confirm the predictive value of the cGAS-STING score and TIICs in the survival prognosis of renal cancers." (PMID 35983076, 2022).
respiratory infections (2 papers, 2022 to 2025). "The cyclic GMP–AMP synthase (cGAS)–stimulator of interferon genes (STING) signaling pathway, a core component of the innate immune system, plays a pivotal role in defending against respiratory infections caused by viruses, bacteria, and mycobacteria, including Mycobacterium tuberculosis." (PMID 40697819, 2025). "The currently ongoing respiratory infections are mostly from RNA viruses such as IAV and SARS‐CoV‐2, which are thought to be sensed by the RNA‐sensing (MDA/RIG‐I) pathway rather than the DNA‐sensing (cGAS/STING) system." (PMID 35313074, 2022).
retina inflammation (2 papers, 2022 to 2026). "This activation, mediated by the cGAS-STING pathway, enhances inflammatory signals and contributes to retinal damage." (PMID 41487469, 2026).
schizophrenia (2 papers, 2023 to 2025). A major psychotic disorder characterized by abnormalities in the perception or expression of reality. "In terms of neural apoptosis, HERV-W env triggers aberrant dopaminergic neuronal processes via DRD2/PP2A/AKT1/GSK3 for schizophrenia risk and promotes antiviral immune response in schizophrenia through the linc01930/cGAS/STING pathway, resulting in neuronal apoptosis." (PMID 40128823, 2025). "Our in-depth study suggested that HERV-W ENV induced innate immune activation and mediated neuronal apoptosis through Linc01930/cGAS/IFN-β axis in the pathophysiology of schizophrenia." (PMID 36769337, 2023). "The totality of these results also showed that HERV-W ENV facilitated antiviral innate immune response, resulting in neuronal apoptosis through the linc01930/cGAS/STING pathway in schizophrenia." (PMID 36769337, 2023).
Streptococcus pneumoniae infection (2 papers, 2022 to 2025). "MyD88 synergizes with the cyclic GMP-AMP synthase-stimulator of interferon genes (cGAS-STING)pathway in Ly6Chi monocytes to enhance IFN-γ production during Streptococcus pneumoniae infection." (PMID 41293166, 2025). "Similarly, Mycobacterium abscessus and Streptococcus pneumoniae infection also lead to the release of mtDNA into the cytosol of murine macrophages, which activates the cGAS-STING-dependent type I IFN production." (PMID 35604097, 2022).
toxoplasmosis (2 papers, 2023 to 2024). A parasitic disease contracted by the ingestion or fetal transmission of toxoplasma gondii. "initially employed mice deficient in cGAS or STING to explore their role in a mouse toxoplasmosis model and found that cGAS is necessary for the activation of anti-T." (PMID 36825026, 2023). "Interestingly, they also found that mice deficient in STING exhibited more severe toxoplasmosis symptoms than cGAS-deficient mice, which suggests that there might be some other sensors getting involved in the activation of STING." (PMID 36825026, 2023). "Furthermore, some intrinsic regulators can be induced during toxoplasmosis and act on cGAS-STING signaling." (PMID 36825026, 2023). "TBK1 is the core kinase in the signaling pathways of cGAS/RLR and TLRs, which is stringently controlled by various PTMs in infectious diseases and cancer, but its role in toxoplasmosis is not well understood." (PMID 39031880, 2024).
vitiligo (2 papers, 2018 to 2025). Generalized well circumscribed patches of leukoderma that are generally distributed over symmetric body locations and is due to autoimmune destruction of melanocytes. "During the course of vitiligo, type I IFNs can be induced by the cGAS–cGAMP–STING pathway after oxidative stress generated DNA damage." (PMID 30515176, 2018).
abortion (1 paper, 2026). the ending of pregnancy by removing a fetus or embryo before it can survive outside the uterus. "In vivo, excessive administration of KYN in pregnant mice increases the rate of embryo resorption, whereas pharmacological inhibition of AHR partially attenuates cGAS-STING pathway activation in dMφs and ameliorates fetal loss in an abortion-prone mouse model." (PMID 41522347, 2026).
acute aortic dissection (1 paper, 2025). "Aortic aneurysm and aortic dissection, both pathologies characterized by smooth muscle cell loss, have also been attributed to the CGAS-STING pathway." (PMID 39861173, 2025). "STING knockout mice demonstrated reduced aortic enlargement and elastic fiber fragmentation compared to a wild-type control in murine models of acute aortic dissection, which may indicate that the cGAS-STING pathway plays a role in aortic VSMC alterations through TBK and IRF-3." (PMID 39861173, 2025).
adenoma (1 paper, 2026). A neoplasm arising from the epithelium. "Downregulation of SLC30A10 in colorectal tubular adenoma is associated with manganese accumulation and alterations in the cGAS-STING pathway, suggesting its potential role in the development and progression of adenoma, a finding with promising research implications." (PMID 41991590, 2026).
adenovirus infections (1 paper, 2023). "The study showed that loss of the cGAS/STING pathway did not affect viral clearance, and cGAS deficiency had a modest influence on the magnitude of the antiviral humoral immune response to adenovirus infections." (PMID 37347197, 2023).
age-related hearing loss (1 paper, 2025). "More recently, the cGAS-STING pathway was shown to mediate interferon I signaling and the inflammatory response in the pathogenesis of age-related hearing loss." (PMID 39676140, 2025). "Melatonin inhibits the cGAS-STING signaling pathway and reduces the expression of cytokines in the cochlea, partially protecting against hearing loss in a presbycusis mouse model." (PMID 39676140, 2025).
AIDS (1 paper, 2023). A syndrome resulting from the acquired deficiency of cellular immunity caused by the human immunodeficiency virus (HIV). "Currently, research has shown that the cGAS-STING signaling pathway is associated with the development and progression of various AIDs." (PMID 37781360, 2023).
airway allergy (1 paper, 2023). "Moreover dsDNA activates the local immune system via the airway dsDNA sensor (cGAS; cyclic GMP-AMP synthase) pathway, which is essential for the induction of airway allergy." (PMID 37772259, 2023).
Airway obstruction (1 paper, 2025). Obstruction of conducting airways of the lung. "Thus, BPE challenge induced AHR, lung inflammation with mucus hypersecretion contributing to airway obstruction which was reduced in the absence of cGAS/STING." (PMID 40276777, 2025).
alcoholic hepatitis (1 paper, 2025). Acute hepatitis resulting from ingestion of alcohol. "In the context of chronic liver diseases, including MASLD and alcoholic hepatitis, persistent heightened activity of the cGAS-STING cascade can exacerbate hepatic inflammation, potentially accelerating disease advancement and even fostering HCC development." (PMID 40098962, 2025).
Alport syndrome (1 paper, 2023). A rare renal disease characterized by glomerular nephropathy with hematuria progressing to end-stage renal disease (ESRD), frequently associated with sensorineural deafness, and occasionally with ocular anomalies. "For in vivo studies we used db/db type 2 diabetes mice as a model of DKD and Col4a3-/- mice as an experimental Alport syndrome model to determine presence and activity of the cGAS-STING pathway in the kidneys." (PMID 37564655, 2023).
ANCA-associated vasculitis (1 paper, 2025). "In the same line it was published that the progression of ANCA-associated vasculitis is dependent on the activation of cGAS/STING/IRF3 axis." (PMID 40111902, 2025).
autosomal dominant tubulointerstitial kidney disease (1 paper, 2025). "Similar results were found in a mouse model of autosomal dominant tubulointerstitial kidney disease due to uromodulin mutations (ADTKD-UMOD), in which cGAS was activated by cytosolic mtDNA." (PMID 40264103, 2025).
Bloom syndrome (1 paper, 2021). Bloom syndrome (BSyn) is a rare chromosomal breakage syndrome characterized by a marked genetic instability associated with pre- and postnatal growth retardation, facial sun-sensitive telangiectatic erythema, increased susceptibility to infections, and predisposition to cancer. "BLM deficiency in Bloom syndrome (BS) causes increased expression of inflammatory genes through the cGAS–STING–IRF3 pathway, suggesting it prevents unchecked inflammatory gene responses." (PMID 34970273, 2021).
brucellosis (1 paper, 2023). Brucellosis is a bacterial infection that spreads from animals to people via unpasteurized dairy products or by exposure to contaminated animal products or infected animals. "In summary, the cGAS/STING pathway induces the production of proinflammatory cytokines after respiratory Brucella infection, which may contribute to the STING-dependent control of airborne brucellosis." (PMID 37261352, 2023). "In this context, the cGAS/STING pathway induces the production of proinflammatory cytokines in lungs and peripheral tissues, which may contribute to the cGAS/STING-dependent control of airborne brucellosis." (PMID 37261352, 2023).
cervical intraepithelial neoplasia (1 paper, 2019). "The promoter methylation levels in cGAS, MAVS, and TRAF3 genes are higher in CPL than in control, indicating that hypermethylation might be an early event in the progression of cervical intraepithelial neoplasia (CIN)." (PMID 31803230, 2019).
Chagas cardiomyopathy (1 paper, 2025). A disease of the cardiac muscle developed subsequent to the initial protozoan infection by trypanosoma cruzi. "The pharmacological inhibition of cGAS using PF-06928215 significantly reduced the production of these pro-inflammatory cytokines, implicating the cGAS/STING pathway in the inflammatory pathogenesis of Chagas cardiomyopathy." (PMID 40497954, 2025).
Chlamydia infection (1 paper, 2024). "To test the role of cGAS in ISG15 induction upon Chlamydia infection, we silenced the expression of this enzyme in HeLa cells before infection." (PMID 39345209, 2024).
choroidal neovascularization (1 paper, 2024). An eye disorder described by the growth of new blood vessels that originate from the choroid through a break in the Bruch membrane into the sub–retinal pigment epithelium (sub-RPE) or subretinal space. "In experimental models of ocular angiogenesis including laser-induced choroidal neovascularization (CNV) and oxygen-induced retinopathy (OIR), the cGAS-STING pathway was activated as angiogenesis progressed." (PMID 38918759, 2024).
Chronic colitis (1 paper, 2021). A chronic inflammatory disease of the large intestine (colon, cecum and rectum). "Therefore, chronic colitis models and human specimens should be considered in future studies to clarify the significance of cGAS in the pathogenesis of human IBD as well as the efficacy and mechanisms of therapeutic candidates (i.e., BFA)." (PMID 34158863, 2021).
chronic lung disease (1 paper, 2024). According to the definitions of the American and British Thoracic Societies, including pulmonary functional tests, X-rays, and CT scans for items such as fibrosis, bronchiectasis, bullae, emphysema, nodular or lymphomatous abnormalities. "Activation of the cGAS-STING-signaling axis, known for its role in promoting inflammation, has been implicated in various acute and chronic lung disease, which most likely involves cellular stress responses to infection." (PMID 39687793, 2024).
chronic pancreatitis (1 paper, 2024). A chronic inflammatory process causing damage and fibrosis of the pancreatic parenchyma. "Third, the cGAS-cGAMP-STING signaling axis is involved in both acute and chronic pancreatitis." (PMID 38169382, 2024).